APOE (apolipoprotein E)
Diseases named in the same sentence as APOE in open-access papers (continued):
Sharing a sentence is not in itself a finding about the gene and the disease.
coronary artery disease (continued). "The response of serum cholesterol to diet may be affected by the apolipoprotein E (APOE) ε2/ε3/ε4 polymorphism, which also is a significant predictor of variation in the risk of coronary heart disease (CHD) and CHD death." (PMID 15571629, 2004). "Thus, the APOC1 genotype may serve as a valuable predictor of APOE status and independently impact LDL cholesterol concentrations, C-reactive protein levels (a common inflammation biomarker), and coronary heart disease risk." (PMID 40722932, 2025). "Notably, APOE and FN1 were associated with coronary artery disease." (PMID 39406990, 2024). "Therefore, we speculate that APOE genotype might affect the severity of coronary artery disease by affecting the lipoprotein profile." (PMID 35209166, 2022). "The PDZK1/apoE dKO mouse model joins a growing list of animal models that share features of classic human coronary heart disease and may thus prove useful for characterizing mechanisms underlying disease development and testing approaches for prevention and treatment." (PMID 19956623, 2009). "Thus, the Paigen diet-fed PDZK1/apoE dKO mice represent a new murine model of coronary heart disease and suggest that PDZK1 may represent a valuable target for therapeutic intervention." (PMID 19956623, 2009). "The interaction between ApoE and ApoC-III on HDL has implications for both metabolism and coronary heart disease." (PMID 37242746, 2023). "A few studies have noticed elevated plasma levels of CCL19 and CCL21 in ApoE-/- mice with AS lesions, human CAP, and patients with coronary artery disease." (PMID 36187128, 2022). "A higher IRF3 profile was seen in macrophages from atheromatous plaques in patients with coronary heart disease (CHD) and ApoE-/- mice." (PMID 36465175, 2022). "Wu and colleagues recently reported that LINC00961 is downregulated in patients with coronary artery disease (CAD) and in APOE–/– mice." (PMID 33478078, 2021). "Furthermore, since higher myeloperoxidase levels were reported in Apo−/− mice, we can postulate that C2238/αANP may, at least in part, associate to higher myeloperoxidase levels, as previously reported in coronary artery disease patients, through its ability to lower ApoE gene expression." (PMID 26720342, 2015). "The calcified lesions were examined by Von Kossa staining in ApoE−/− mice which were fed high fat diets (HFD) for 48 weeks and human subjects aged 60 years and older that had died of coronary heart disease, heart failure or acute renal failure." (PMID 26148272, 2015). "In this study, we describe a new murine model of diet-induced coronary heart disease, the Paigen-diet-fed PDZK1/apoE dKO mouse." (PMID 19956623, 2009). "In obese and coronary artery disease patients, high levels of HDL containing apoE but lacking apoCIII are associated with reduced coronary plaque burden and cardiovascular risk, whereas HDL containing both apoE and apoCIII are associated with increased disease burden and cardiovascular risk." (PMID 38879166, 2024). "However, atherogenic diet-fed SR-B1 KO/ ApoER61h/h or double SR-B1/apoE KO mice represent a valuable tool considering that not many models of coronary heart disease and its ischemic complications, including heart failure and death, are available." (PMID 30219096, 2018). "The effect of ApoE on AMD risk is not consistent with findings in AD and ischemic heart disease." (PMID 21822496, 2011).
endothelial dysfunction (186 papers, 2009 to 2026). In vascular diseases, endothelial dysfunction is a systemic pathological state of the endothelium (the inner lining of blood vessels) and can be broadly defined as an imbalance between vasodilating and vasoconstricting substances produced by (or acting on) the endothelium. "Compared to the more common APOE ε3 allele, ε4 is associated with impaired clearance of remnant lipoproteins and increased oxidative stress, further contributing to endothelial dysfunction and vascular inflammation." (PMID 40671162, 2025). "Our findings demonstrated that psEVs alone were sufficient to induce inflammatory endothelial dysfunction in vitro and exacerbate atherogenesis in ApoE‐deficient mice." (PMID 40391195, 2025). "Single-cell RNA sequencing further reveals endothelial dysfunction as a key mechanism underlying sex-dimorphic APOE ε4 effects." (PMID 41409615, 2025). "Liraglutide has also been found to improve plaque stability and hinder atherosclerotic plaque development in apolipoprotein-E-deficient (ApoE−/−) mice by suppressing endothelial dysfunction and the expression of vascular adhesion molecules." (PMID 35739957, 2022). "For example, it was demonstrated that inflammation in the PVAT and adventitial layer happened prior to the development of endothelial dysfunction and formation of atherosclerotic plaques in apolipoprotein E-deficient (ApoE−/−) mice." (PMID 35177953, 2022). "Chronic Ang IV treatment reverses endothelial dysfunction in apolipoprotein E- (ApoE-) deficient mice." (PMID 34950416, 2021). "We further showed that exercise training ameliorated ER stress-associated endothelial dysfunction in coronary arterioles in ApoE KO mice by reducing ER stress and TXNIP/NLRP3 inflammasome signaling." (PMID 34326395, 2021). "Lastly, we determined that exercise training rescued UCP2 deficiency-mediated endothelial dysfunction in coronary arterioles of ApoE KO via down-regulation of ROS by means of up-regulating UCP2 expressions." (PMID 34326395, 2021). "The main finding was that endothelial dysfunction in male ApoE KOs on a Western diet was associated with changes in COX-dependent signaling in pulmonary arteries despite no detectable changes in the protein expression of COX-1 and -2." (PMID 32943715, 2020). "For instance, chitin with glucan and polyphenols from pomegranate recovered endothelial dysfunction by reducing inflammatory marker in the liver and adipose tissues and promoting NO synthase in apolipoprotein E deficient mice (apoE−/−) with high fat diet." (PMID 33339290, 2020). "We have previously shown that a single simulated dive causes endothelial dysfunction in the pulmonary arteries of male ApoE knockout rats." (PMID 33424633, 2020). "Endothelial dysfunction in the pulmonary arteries of ApoE KO rats was associated with altered production or bioavailability of NO and was more profound in male than in female rats." (PMID 33424633, 2020). "Our study demonstrates that chronic apolipoprotein E deficiency promotes endothelial dysfunction in retinal arterioles." (PMID 31781340, 2019). "In summary, endothelial dysfunction after a single dry heliox dive was associated with changing in bioavailability of NO in males, and altered prostanoid signaling in female ApoE KO rats." (PMID 31695628, 2019). "The main finding of this study was that simulated diving caused endothelial dysfunction in the pulmonary arteries of ApoE KO rats." (PMID 31695628, 2019). "Lower eNOS and nNOS activation is also related to endothelial dysfunction in apolipoprotein E-deficient mice." (PMID 29615924, 2018). "Taken as a whole, the results of this study suggest that exercise training acts as a significant moderator of endothelial dysfunction by attenuating ER stress and ER stress-associated inflammation and oxidative stress in mesenteric arteries of ApoE KO mice." (PMID 29784903, 2018).
endothelial dysfunction (continued). "Since ApoE polymorphism is a key player in lipid metabolism, it is possible that it leads to susceptibility to endothelial dysfunction and atherogenesis." (PMID 26790728, 2016). "According to our data, it has been previously observed that SOD improves endothelial function and Mn-SOD protects against oxidative stress and endothelial dysfunction in ApoE-deficient mice." (PMID 26635913, 2016). "In summary, CIT enhances atherogenesis in hypercholesterolemic apoE-deficient mice via upregulating inflammation and endothelial dysfunction." (PMID 25933220, 2015). "This study investigated the contribution of OCN to the pathogenesis of endothelial dysfunction in the thoracic aorta of apolipoprotein E-deficient (ApoE-KO) mice." (PMID 24708830, 2014). "In contrast to diabetic ApoE−/−/AT1R−/−-mice, endothelium dependent vasodilatation was significantly impaired in diabetic ApoE−/−-mice indicating that AT1R-deficiency attenuates endothelial dysfunction in diabetic animals." (PMID 23374104, 2013). "Recently, we reviewed the potential mechanisms underlying endothelial dysfunction in the apoE-/- mouse and how endothelial dysfunction is influenced by aging, gender and diet." (PMID 22330242, 2012). "In apoE-/- mice endothelial dysfunction is associated with increased •O2- and decreased eNOS activity." (PMID 22082357, 2011). "Chronic administration of BMS309403, a small molecule FABP4 inhibitor, significantly improved endothelial dysfunction in ApoE-deficient mice." (PMID 22121495, 2011). "Specifically, we discuss the main mechanisms underlying endothelial dysfunction in the apoE-/- mouse and examine how this vascular defect can be influenced by diet, aging and gender." (PMID 22082357, 2011). "The mechanism of endothelial dysfunction in ApoE-/- mice involves both decreased bioavailability of NO caused by superoxide anion radicals and degradation of the eNOS cofactor tetrahydrobiopterin." (PMID 22074227, 2011). "Second, we discuss the main mechanisms underlying the endothelial dysfunction of conducting vessels and resistance vessels and examine how this vascular defect can be influenced by diet, aging and gender in the apoE-/- mouse." (PMID 22082357, 2011). "On the other hand, studies in resistance vessels from ApoE-deficient mice have shown normal endothelial function in males and endothelial dysfunction in females." (PMID 20482882, 2010). "In the present study, we show that the isolated mesenteric arteriolar bed of female ApoE-deficient mice fed a normal diet also presents endothelial dysfunction, as indicated by the marked decrease in ACh-induced vasorelaxation." (PMID 20482882, 2010). "Contrasting with males, we observed that female ApoE-deficient mice on a normal chow diet show endothelial dysfunction of resistance vessels." (PMID 20482882, 2010). "Studies in conductance vessels of male and female ApoE-deficient mice have shown both normal endothelial function and endothelial dysfunction." (PMID 20482882, 2010). "A recent report demonstrated that ezetimibe treatment attenuated vascular functions, such as endothelial dysfunction, oxidative stress, and inflammation in high-fat fed apoE-deficient mice." (PMID 19821987, 2009). "Indeed, the slow-release hydrogen sulfide donor GYY4137 has been shown to decrease oxidative stress and lipid accumulation and to restore endothelial dysfunction in high-fat-fed apolipoprotein-E-deficient mice." (PMID 37108182, 2023). "The associations between IC and E-selectin, allostatic load and ApoE ε4 genotype suggested the underlying biological features of IC, indicating that mental health issues and endothelial dysfunction may be of greater impact in the biology of IC." (PMID 35308493, 2022). "A-FABP could reduce the insulin-dependent nitric oxide synthase (NOS) expression in human umbilical vascular endothelial cells, while A-FABP inhibitor improves endothelial dysfunction in old ApoE-deficient mice." (PMID 33628486, 2021).
endothelial dysfunction (continued). "Apolipoprotein E deficiency induces oxidative stress and endothelial dysfunction in retinal arterioles, which may trigger hypoxia in the retinal tissue." (PMID 31781340, 2019). "In this study, we hypothesized that simulated diving in arteriosclerosis-prone ApoE KO rats would cause endothelial dysfunction in pulmonary circulation, and that this deterioration would be larger in pulmonary than in peripheral, e.g., mesenteric, arteries." (PMID 31695628, 2019). "In addition, WTD-fed ApoE KO mice also caused endothelial dysfunction as evidenced by decreased ACh-induced vascular tone and increased ET-1 expression." (PMID 24062791, 2013). "The physiological importance of SOD2 is high-lighted by the finding that in contrast to other SOD isoforms, the deficiency of SOD2 causes early neonatal death in gene knockout mice and endothelial dysfunction in carotid artery of proatherogenic apolipoprotein E (ApoE)-deficient mice." (PMID 23442817, 2013). "The main potential mechanism underlying the endothelial dysfunction of apoE-/- mice may be the endothelial NO synthase (eNOS) pathway, due to the uncoupling of eNOS in the endothelium." (PMID 22330242, 2012). "In the present study, the eNOS level was measured in order to understand whether CS-mediated emphysema in ApoE-/- mice was associated with endothelial dysfunction." (PMID 20663150, 2010). "We speculate that increased superoxide anion production and reduced activity of endothelial nitric oxide synthase could contribute to the endothelial dysfunction in female ApoE-deficient mice." (PMID 20482882, 2010). "Therefore, we would test the hypothesis that ethanol-binge drinking-induced protein S-glutathionylation causes aortic endothelial dysfunction in ApoE−/− mice." (PMID 33796575, 2021). "Therefore, the aim of this study was to investigate whether periodontitis induces endothelial dysfunction in hyperlipidemic apolipoprotein E gene-deficient (ApoE-/-) mice." (PMID 34294791, 2021). "we reveal a female-specific APOE ε4-driven molecular network linking endothelial dysfunction to tau pathology." (PMID 41409615, 2025). "The initial atherosclerotic mouse models focused on atherogenesis, seen typically in ApoE−/− mouse models as they are used to study endothelial dysfunction due to their ability to develop atherosclerotic lesions spontaneously." (PMID 38704690, 2024). "Conversely, the expression of NOX1 and NOX2 proteins exhibited upregulation specifically within the endothelium of the ApoE−/− mouse aorta, implying their involvement in the generation of ROS and subsequent endothelial dysfunction." (PMID 37873768, 2023). "For example, the increase in luminal diameter to 10−4 M acetylcholine was 26 ± 11% and 67 ± 9.7% (p < 0.01) in ApoE−/− and wild-type mice, respectively, indicative of endothelial dysfunction in the ApoE−/− mouse aorta." (PMID 37873768, 2023). "In the present study, the HFD contributed to a significant increase in serum ET-1 levels in apoE−/− mice, indicative of endothelial dysfunction." (PMID 36853380, 2023). "GDF11 was also shown to improve endothelial dysfunction, inhibit endothelial apoptosis, and reduce atherosclerotic plaque in apolipoprotein E knockout (ApoE KO) mice." (PMID 35012677, 2022). "Recently, vascular functional studies have shown that ER stress is a critical player in endothelial dysfunction by reducing eNOS expression and NO bioavailability in ApoE KO mice and other pathological animal models." (PMID 34326395, 2021).
endothelial dysfunction (continued). "We induced periodontitis in ApoE-/- mice by oral lavage with P. gingivalis and S. gordonii and provide evidence that periodontitis resulted in endothelial dysfunction within a period of 4 weeks." (PMID 34294791, 2021). "In apolipoprotein E-deficient mice (ApoE(−/−) mice), the deletion of SIRT6 via lentivirus injection accelerated endothelial dysfunction and atherosclerosis." (PMID 33436551, 2021). "In this work, endothelial dysfunction was induced in HFD fed ApoE-/- mice, as demonstrated by the decrease of serum NO level as well as the increase of the adhesion molecule (E-selectin, ICAM-1 and VCAM-1) and chemokine (MCP-1) expression in the aorta." (PMID 34769040, 2021). "Therefore, the current study design investigated whether induction of periodontitis in hyperlipidemic apolipoprotein E gene-deficient (ApoE-/-) mice promotes systemic inflammation and endothelial dysfunction, prior to the development of extensive atherosclerotic lesions." (PMID 34294791, 2021). "While in vivo, both adult and aged ApoE−/− mice chronically administered with DAPA showed attenuated endothelial dysfunction and less vascular adhesion molecules." (PMID 34884494, 2021). "APOE genotype can affect the efficiency of this drainage pathway, through differences in Aβ–apoE interactions, also enhancing endothelial dysfunction." (PMID 34066951, 2021). "Treating WD-fed apoE−/− mice with LOE improves endothelial dysfunction by reducing NADPH oxidase expression and the formation of ROS." (PMID 34834858, 2021). "It seems that survivin can interfere with the elongation of autophagosomes in ECs and prevent excessive autophagy, apoptosis and/or senescence following endothelial dysfunction in GDF-15−/−/ApoE−/− mice after 20 weeks CED." (PMID 34571994, 2021). "ApoE−/− mice developed severely impaired endothelium-dependent vasodilation, indicating endothelial dysfunction." (PMID 34422919, 2021). "Empagliflozin ameliorated the RNA expression of inflammatory factors in PVAT, attenuated diabetes-induced endothelial dysfunction, and decreased the atherosclerotic lesion area in the aortic arch of diabetic ApoE–/– mice." (PMID 33391033, 2020). "Our findings suggest that small arteries from ApoE KO rats develop endothelial dysfunction prior to the development of atherosclerotic lesions." (PMID 32943715, 2020). "We showed that male ApoE KOs on a high-fat Western diet developed endothelial dysfunction via changes in COX-dependent relaxation and increased production of endothelium-derived contractile factors." (PMID 33424633, 2020). "We demonstrated that HF feeding for 8 weeks accelerated the process of endothelial dysfunction in resistance mesenteric arteries in ApoE−/− genotype, as already shown in previous studies." (PMID 31578395, 2019). "Male Apolipoprotein E knock-out (ApoE−/−) mice fed a high fat (HF) diet developed a significant endothelial dysfunction attested by atherosclerotic plaques and increasing abundance of caveolin-1 in aorta." (PMID 31578395, 2019). "Studies have shown an improvement of endothelial dysfunction by enhancing NOS-III expression in a rat model of pulmonary hypertension and in apolipoprotein E (ApoE)–deficient mice." (PMID 31071151, 2019). "A single simulated dive was found to induce endothelial dysfunction in the pulmonary arteries of ApoE KO rats, and this was more profound in male than female rats." (PMID 31695628, 2019). "In contrast to incubation in the presence of indomethacin, this effect disappeared in the presence of NO synthase inhibitor, suggesting that HF diet worsened the NO-dependent endothelial dysfunction of ApoE−/− in mesenteric arteries." (PMID 31578395, 2019). "Mesenteric arteries isolated from HF treated ApoE−/− mice relaxed less in response to acetylcholine than vessels obtained from ApoE−/− mice fed a control diet, suggesting the presence of endothelial dysfunction in HF fed mice whatever the supplementation." (PMID 31578395, 2019).